RNU7-95P (RNA, U7 small nuclear 95 pseudogene)
Gene: Small nuclear RNA gene on chromosome 1 (53,688,749 to 53,688,812, reverse strand). Ensembl gene ENSG00000239007.
Homologues: Orthologues: chimpanzee U7 (97% identical), macaque U7 (91% identical). Paralogues in human: U7 (81% identical), RNU7-127P (80% identical), RNU7-37P (80% identical), RNU7-70P (80% identical), RNU7-34P (78% identical), RNU7-40P (78% identical), RNU7-62P (78% identical), RNU7-73P (78% identical), RNU7-130P (77% identical), RNU7-188P (77% identical), RNU7-55P (77% identical), RNU7-7P (77% identical), and 142 more.